SF3B1 (splicing factor 3b subunit 1)
Diseases named in the same sentence as SF3B1 in open-access papers (continued):
Sharing a sentence is not in itself a finding about the gene and the disease.
cancer (continued). "We also found that cancer-related functions such as cell division, regulation of cell cycle, DNA replication, and response to UV were included in altered AS by SF3B1, indicating that wild-type SF3B1 might also play important roles in cancer." (PMID 33317029, 2020). "In contrast, the loss of the commonly mutated cancer target SF3B1 appeared to be toxic to non-malignant cells as well." (PMID 32545483, 2020). "In addition, there appears to be a connection between splicing factor protein SF3B1 mutations and BRD9 degradation in cancers like myeloid leukemia, lymphoid leukemia, and uveal melanoma." (PMID 33143733, 2020). "Both neurofibromin and SF3B1 have been identified as oncogenic drivers in a variety of cancers." (PMID 31466283, 2019). "In this study another aspect of SF3B1 in cancer has been suggested." (PMID 29954402, 2018). "Our finding that SF3B1 can regulate HSF1 concentration could have profound implications for cancer biology." (PMID 28445500, 2017). "To validate whether JA regulates the cancer spliceosome, we carried out immunoblotting to confirm the expression of SF3B1 and SF3B3 following JA treatment in MCF-7 and MDA-MB-468 cells." (PMID 28198434, 2017). "Furthermore, as was recently described for human cancer samples, we show that aberrant BP recognition is central to the disrupted function of mutant SF3B1 in our mice." (PMID 27604819, 2017). "Therefore, it is possible that similar approaches to targeting the spliceosome can be exploited in SF3B1-mutant and SF3B1loss cancers." (PMID 28177281, 2017). "In addition, depletion of splice factors including SNRPD3, SF3B1, and XAB2 in cancer cells was found to cause defects in sister chromatid cohesion via aberrant splicing of soronin pre‐mRNA." (PMID 28296343, 2017). "Although SF3B1 did not meet the significance threshold in this cohort, it is a known cancer gene that is also recurrently mutated in UM." (PMID 28594900, 2017). "However, it is also possible that alternative strategies will be required for SF3B1-mutant and SF3B1loss cancers, due to their different effects on spliceosome assembly and activity." (PMID 28177281, 2017). "SF3B1 expression was demonstrated in different TCGA carcinoma study groups." (PMID 29383138, 2017). "As such, BV-6 may represent a therapeutic opportunity for patients with SF3B1 mutant cancers." (PMID 40595498, 2025). "Additionally, unlike both SUGP1 and DHX15, DDX46 is not known to harbor any cancer-associated mutations that recapitulate mutant SF3B1 missplicing." (PMID 37977822, 2023). "Multiple studies have found that the SF3B1 mutation uses an alternative cryptic 3’-splice site (3’Alternative Splice Site, A3SS) during splicing, which may be a potential mechanism for its induction of splicing alterations in cancers such as MDS." (PMID 37007111, 2023). "Likewise, among the five SUGP1 cancer-associated residues, only R625 and P636 were predicted to have direct interactions with SF3B1, while the other three (L515, G519, and R642) were not (although embedded in the interface)." (PMID 37977822, 2023). "SF3B1 blockade also exerted important molecular actions involving the splicing modulation of two clinically relevant SVs of BCL2L1 (Bcl-xL and Bcl-xS) associated with cancer -development and known to play an oncogenic role and a tumor suppressor actions, respectively." (PMID 35086552, 2022). "Herein, we demonstrated that SF3B1 dysregulation clearly affects several cancer hallmarks including apoptosis/proliferation/migration/angiogenesis/splicing pattern and signaling among others, and, of particular clinical relevance, that it could be associated with the development of drug resistance." (PMID 35086552, 2022). "We could confirm mis-splicing and downregulation of BRD9 in SF3B1-mutated cancers, but neither mis-splicing nor downregulation of BRD9 was detected for ASB-CLL." (PMID 36266272, 2022).
cancer (continued). "Importantly, the SF3B1 inhibitor FR901464 plays an anticancer role in a variety of cancers." (PMID 35210412, 2022). "Finally, we demonstrate that SLED-based AAV constructs perform as efficiently as state-of-the-art minipromoter vectors for functional rescue of photoreceptor dystrophies, and also show that SLED can be used to selectively target SF3B1 mutant cancer cells for oncolytic therapy." (PMID 36182931, 2022). "This indicated that inhibition of wild type SF3B1 is likely cytotoxic, also in cells lacking oncogenic SF3B1 mutations; and, since all SF3B1 mutant cancers are heterozygous, selective inhibition of mutant SF3B1 might not have strong therapeutic effects." (PMID 34065983, 2021). "Hence, SF3B1 appeared an essential gene and SF3B1 mutations in cancer cells, at least the ones investigated, were not essential for cancer cell growth." (PMID 34065983, 2021). "Over the past decade, SF3B1, SRSF2, U2AF1 and ZRSR2, splicing factors that are involved in early intron selection and pre-spliceosome assembly, have been identified as the most frequently mutated splicing factors in cancers based on the fast-developing next-generation sequencing techniques." (PMID 34723968, 2021). "Mutations in SF3B1, SRSF2, and U2AF1 are concentrated as heterozygous mutations at the site coding for a particular amino acid, called a hot spot, and promote carcinogenesis or cancer progression by causing mis-sense mutations that alter the gain or alteration of the functional form of the protein." (PMID 33923658, 2021). "In the present study, we not only show that the pivotal splicing machinery component SF3B1 is overexpressed in PDAC, but it can be targeted by Pladienolide-B, which causes antioncogenic effects in both cancer cells and CSCs, paving the way to develop new treatment strategies for this deadly cancer." (PMID 34857016, 2021). "To date, it remains unclear what functional role SF3B1 mutations play in carcinogenesis, and it has not been well established whether deregulated SF3B1 activity is required for the maintenance of cancer." (PMID 32905346, 2020). "Thus, SF3B1 not only has roles in cancer, but also has roles in genetic diseases." (PMID 33317029, 2020). "Therefore, we examined whether SF3B1 is secreted as an exosomal component from HCC by analyzing exosomes derived from HCC cancer cell lines." (PMID 29954402, 2018). "How SF3B1 and HSF1 influence each other in the highly mutated landscape of a transformed cell and how the relationship between SF3B1 and HSF1 are affected in different malignancies could provide valuable clues to basic systems biology and to cancer biology." (PMID 28445500, 2017). "Post-treatment samples may also acquire mutations in known cancer driver genes (for example, SF3B1, TAF1 and CCND2) that are absent from the paired pre-treatment sample." (PMID 27045317, 2016). "We found that cryptic 3’SS selection is limited to tumors with mutations in the five ~10 amino acid hotspots in the SF3B1 HEAT 5–9 repeats and that these mutations are associated with cryptic 3’SS selection across different cancer types and even in cancers in which SF3B1 is not recurrently mutated." (PMID 25768983, 2015). "We show that cancers with mutations in the SF3B1 HEAT 5-9 repeats use cryptic 3’SSs downstream of the branch point and provide both a mechanistic model consistent with published experimental data and affected targets that will guide further research into the oncogenic effects of SF3B1 mutation." (PMID 25768983, 2015). "Interestingly, 2 out of 24 (8.3%) mucinous carcinomas of the breast annotated in the data were identified as having SF3B1 K700E mutations and lacked mutations in additional significantly mutated genes or known cancer genes." (PMID 25424858, 2015).
cancer (continued). "For example, CD44, ARIH2, CSDE1 (also known as UNR), CYB5B, SF3B1, and RCN2, which have been reported to be overexpressed in cancer, showed an increased proportion of shorter 3′-UTRs, primarily as a result of alternative cleavage and polyadenylation (APA)." (PMID 40702779, 2025). "In detail, BRD9 was located together with other known cancer dependencies, including PIK3R1, EZH2, and FBXW7, whereas SF3B1 had a very high efficacy but low selectivity." (PMID 39261602, 2024). "SF3B1 and SF3B7 (also known as PHD finger protein 5A, PHF5A) have been extensively investigated for their functional roles in multiple cancers, including CRC." (PMID 38671459, 2024). "Since the MYC‐driven increase in transcription overloads proper pre‐mRNA splicing, the depletion or pharmacological inhibition of core spliceosome components, including SF3B1, is detrimental for MYC‐dependent cancer cells." (PMID 36855776, 2023). "Additional amplifications were found in other cancer-related genes including ARAF, SF3B1 in CTCs and KIT in cfDNA." (PMID 35269713, 2022). "Studies have shown that SF3B1, SF3B2, and SF3B3 can regulate target gene expression by alternative splicing to promote cancer progression." (PMID 35210412, 2022). "Accordingly, IHC staining of 18 randomly selected samples from this same cohort revealed SF3B1 nuclear immunostaining in NTAT (acinar and ductal cells) and cancer cells, where the staining score was higher." (PMID 34857016, 2021). "SF3B1 expression was first evaluated in adherent (ADH) and spheroid (SPH) cell cultures derived from these cell lines, which represent, respectively, cancer- and CSC-enriched cell populations from the corresponding PDXs." (PMID 34857016, 2021). "RSMs are exemplified by SF3B1 K700E, which was mostly observed in BRCA patients (9/15), but sporadic cases were observed in other cancer types (LAML, PRAD, SARC, SKCM and THYM) with low frequency." (PMID 31925297, 2020). "Since 2011, recurrent somatic mutations have been identified in a number of spliceosome components in human malignancies through the Cancer Genome Project, such as U2AF1 (U2AF35), SRSF2 (SC35), SF3B1 (SF3B155 or SAP155), and ZRSR2 (URP)." (PMID 32905346, 2020). "SF3B1 is a target of PLAD-B, a natural product with anti-tumor activity in both cancer cell lines and mouse xenograft models." (PMID 33040078, 2020). "Hence, though seemingly disparate, as SF3B1 is characterized as an RNA-splicing protein and neurofibromin as a Ras pathway protein, our finding that these proteins physically interact provides further evidence that they play a role in a common pathway leading to these types of cancers." (PMID 31466283, 2019). "Exosomes from the HepG2 or Huh7 cancer cells were collected by ultracentrifugation and probed with XC24 as well as with commercial anti-SF3B1 antibody." (PMID 29954402, 2018). "The intriguing link between the mRNA splicing machinery and the heat shock response and the important roles of both SF3B1 and HSF1 in cancer prompted us to further analyze the connections between SF3B1 and the HSR." (PMID 28445500, 2017). "An overall downregulation of cancer hallmark genes was found when splicing factors such as SRSF2 and SF3B1 were mutated in UM, unlike other kinds of cancers." (PMID 38920653, 2024). "Research has shown that certain components of spliceosomes, including U1 snRNA, SF3B1, and U2AF1, may be related to tumors, which are critically involved in cancer progression." (PMID 39507054, 2024).
cancer (continued). "While it is known that SF3B1 hotspot mutations lead to loss of splicing factor SUGP1 from spliceosomes, the cancer-relevant SF3B1–SUGP1 interaction has not been characterized." (PMID 37977822, 2023). "Our studies show that CHEK2 is a critical SF3B1 target, as ectopic expression of CHEK2 demonstrates high synergy of SF3B1 inhibitors with CHEK2 inhibitors as well as chemotherapeutic drugs, and propose that the SF3B1 inhibitor E7107 is a lead compound that sensitizes cancer cells to chemotherapy." (PMID 35061527, 2022). "We conclude that SF3B1 overexpression represents a therapeutic vulnerability in PDAC that enables the targeting of splicing with Pladienolide-B not only in cancer cells but also in CSCs, which opens up novel therapeutic avenues for this lethal cancer." (PMID 34857016, 2021). "SF3B1 overexpression represents a therapeutic vulnerability in PDAC, as altered splicing can be targeted with Pladienolide-B both in cancer cells and CSCs, paving the way for novel therapies for this lethal cancer." (PMID 34857016, 2021). "The SF3B1 modulators have promising cytotoxic activity, which is enhanced in cancer cells as compared to non-malignant cells, while retaining activity against (multi-) drug resistant cells." (PMID 34356101, 2021). "Several studies suggest that these targets represent cancer-selective vulnerabilities, as opposed to much investigated targets such as the U2 snRNP specific component SF3B1." (PMID 34065983, 2021). "They suggest that SF3B1 is a promising novel druggable target as well as a prognostic biomarker in HCC, as has been reported in other malignancies, such as pancreas, breast, and prostate cancers." (PMID 35008179, 2021). "In addition, we found in this list established cancer genes involved in other types of cancer, such as PDE4DIP, SF3B1, AHNAK, COPB2, CSDE1, KIF5B, NDUFA10, RSRC2." (PMID 31949199, 2020). "The FIR-SAP155 (SF3B1) interaction affects both hnRNPA1 and c-Myc expression and may represent a therapeutic target in c-Myc-driven cancer." (PMID 28978087, 2017). "The identification of SF3B1 as a CYCLOPS gene highlights a previously unrecognized cancer vulnerability and implicates non-driver alterations of wild-type SF3B1 as a potential therapeutic target present in 11% of all cancers." (PMID 28177281, 2017). "Genomic deletions of SF3B1 typically affect most of the chromosome arm (81% of losses) and are never homozygous (0/10,570 cancers), consistent with characterization of SF3B1 as an essential gene." (PMID 28177281, 2017). "The mutant SF3B1 causes a truncated, most likely nonfunctional, SVCT2 that can result in intracellular deficiency of vitamin C in cancer cells." (PMID 25977731, 2015). "Our finding that mutations in the splicing factor machinery can result in increased splicing antigenicity in some cancers relative to wild-type samples is complemented by this study even though SF3B1 does not reach BH-adjusted P value significance in our study." (PMID 39470352, 2024). "However, how SF3B1 and SUGP1 interact is not known, leaving gaps in our understanding of both how branch sites and 3′ splice sites are correctly selected and how cancer mutations disrupt this process." (PMID 37977822, 2023). "The finding that a DUBi specifically suppresses growth of cells with loss of SF3B1 also supports the use of DUBi’s to target any of the 124 candidate CYCLOPS genes we identified, representing a potential paradigm for treating cancers based upon non-oncogenic genetic events." (PMID 28177281, 2017). "However, both higher levels of Pladienolide B and SF3B1 siRNA knockdown also change the concentration of HSF1, a form of HSR regulation that has not been previously documented during normal physiology but is observed in some forms of cancer." (PMID 28445500, 2017).
cancer (continued). "However, based on the distinct mechanism of JA in stabilizing SF3B1, rather than inhibition as demonstrated by other spliceosome modulators, it is likely that JA might engage a novel mechanism to regulate the cancer spliceosome activities." (PMID 28198434, 2017). "As we identified Sm proteins, but not SF3B1, as cancer-selective lethal targets in NSCLC, we sought to identify AS events that occur in NSCLC cells exclusively upon Sm silencing compared to SF3B1." (PMID 32545483, 2020). "Interestingly, the analysis revealed that 7 targets (SF3B1, SF3B3, SNRPA, SNRPE, SNRPF, HNRNPA3 and EFTUD2) are physically interacting proteins within the spliceosome complex, suggesting that JA might regulate the cancer spliceosome to induce tumor-specific cell death." (PMID 28198434, 2017).